RAD51 (RAD51 recombinase)
Diseases named in the same sentence as RAD51 in open-access papers (continued):
Sharing a sentence is not in itself a finding about the gene and the disease.
metastatic disease (4 papers, 2016 to 2022). "The missense mutations in RAD51 could be drivers of lung and kidney cancers and metastatic diseases." (PMID 29697361, 2018). "The patient from whom this mutation was identified developed aggressive metastatic disease, therefore we postulated that RAD51 G151D may have contributed to the acquisition of the invasive and eventual metastatic behavior of the tumor cells." (PMID 27513445, 2016). "In total, our data lead us to conclude that RAD51 G151D expression directly contributed to the therapeutic resistance of the primary and metastatic tumors in the patient." (PMID 27513445, 2016).
oral cancer (4 papers, 2020 to 2023). "High RAD51 protein expression in oral cancer tissues had a poor impact on the OS of OSCC patients receiving adjuvant chemotherapy and a significantly negative influence on the PFS of OSCC patients receiving adjuvant radiotherapy." (PMID 37798649, 2023). "A small-molecule inhibitor of RAD51, B02, significantly sensitized oral cancer cells to cisplatin treatment." (PMID 37798649, 2023). "Oral cancer cells with higher RAD51 protein expression survived better after treatment with different chemotherapeutic agents, including cisplatin, mitomycin, and bleomycin, and after irradiation." (PMID 37798649, 2023). "Another oral cancer cell line CAL27 also revealed similar result that RAD51 OE cells survived better after cisplatin and mitomycin treatment." (PMID 37798649, 2023). "RAD51 expression in different oral cancer cell lines (Ca9-22, CAL27, SAS, HSC-3, and OECM1) was determined by western blotting." (PMID 37798649, 2023). "We also investigated the influence of RAD51 expression on the biological behavior of oral cancer cells." (PMID 37798649, 2023). "RAD51 overexpression promotes resistance to chemotherapy and radiotherapy in oral cancer cells in vitro." (PMID 37798649, 2023). "Co-treatment with RAD51 inhibitor B02 and cisplatin, compared with cisplatin alone, significantly enhanced cytotoxicity in oral cancer cells." (PMID 37798649, 2023). "We also compared RAD51 expression in oral mucosa epithelial cells (OMECs), keratinocytes, and tongue squamous cell carcinoma cells (TSCCs) to provide a theoretical basis for the clinical use of RAD51 as a prognostic biomarker for oral cancer." (PMID 32190537, 2020). "This suggested that RAD51-mediated treatment resistance in oral cancer occurs through mechanisms other than stem cell signaling and the role of RAD51 in the resistance to chemotherapy and radiotherapy requires further exploration, for example whole genome sequencing in the future." (PMID 37798649, 2023). "However, studies on the relationship between RAD51 and alcohol consumption in oral cancers require further investigation." (PMID 37798649, 2023). "The influence of RAD51 on the biological profile of oral cancer cells was evaluated." (PMID 37798649, 2023). "Higher tumorsphere formation ability was observed in RAD51 overexpressing oral cancer cells." (PMID 37798649, 2023). "Therefore, we chose SAS to knockdown RAD51 expression and OECM1 to overexpress RAD51 by lentivirus transduction to analyze the function of RAD51 in oral cancer cells." (PMID 37798649, 2023). "In oral cancer, high levels of MRE11 and RAD51 correlated with radiation resistance and poor prognosis." (PMID 37894339, 2023).
oral squamous cell carcinoma (4 papers, 2020 to 2025). "RAD51 protein expression, assessed by immunohistochemical staining, was used to examine associations with survival and clinicopathological profiles of patients with oral squamous cell carcinoma." (PMID 37798649, 2023). "To begin, we validated the mRNA expression of RAD51 in oral squamous cell carcinoma (OSCC) compared to normal tissues using three independent datasets from the GEO database: GSE37991, GSE74530 and GSE23558 (p < 0.05)." (PMID 41350246, 2025). "Compared to the normal human oral keratinocyte cell line HOK, both qRT‐PCR and western blotting assays demonstrated significantly elevated RAD51 mRNA and protein levels in oral squamous cell carcinoma (OSCC) cell line HSC‐3." (PMID 41350246, 2025). "Oral squamous cell carcinoma patients with higher RAD51 expression exhibited worse survival, especially those treated with adjuvant chemotherapy and radiotherapy." (PMID 37798649, 2023). "This study, through multiomics analysis and experimental validation, discovered that RAD51 is significantly overexpressed in oral squamous cell carcinoma (OSCC) and drives tumour progression by promoting malignant phenotypes, suppressing immune infiltration and inducing dysregulated DNA repair." (PMID 41350246, 2025). "RAD51 is a poor prognostic marker for oral squamous cell carcinoma." (PMID 37798649, 2023). "This study aimed to survey the role of RAD51 in oral squamous cell carcinoma and whether RAD51 could be a potential therapeutic target." (PMID 37798649, 2023).
pancreatic ductal adenocarcinoma (4 papers, 2015 to 2026). An infiltrating adenocarcinoma that arises from the epithelial cells of the pancreas. "Pancreatic ductal adenocarcinoma is a cancer type where overexpression of Rad51 has been described." (PMID 25994202, 2015). "JQ1 was reported to induce DNA double strand breaks in pancreatic ductal adenocarcinoma, but at the same time to also decrease the expression of DNA repair proteins such as KU80 (Ku Autoantigen 80) and RAD51." (PMID 33803654, 2021). "Notably, several of the genes affected by Cr(VI) exposure such as MLH1, RAD51, CD44, and Nupr1 are well-recognized contributors to pancreatic ductal adenocarcinoma (PDAC) development." (PMID 42039696, 2026).
renal cell carcinoma (4 papers, 2016 to 2024). "Here, we report a case of renal cell carcinoma in patient with concurrent germline mutations in BRCA1 and RAD51 genes." (PMID 38512353, 2024). "Moreover, the interference of PDIA6 increased phosphorylation of H2A histone family member X (γH2AX), while decreased Rad51 and phosphorylated DNA-dependent protein kinase (DNA-PK) (p-DNA-PK) in imatinib-resistant renal cell carcinoma cells." (PMID 34781823, 2021). "Knockdown of PDIA6 down-regulated protein expression of p-DNA-PK and Rad51 in A498/R post incubation with imatinib, revealing that PDIA6 contributed to the DNA damage repair of imatinib-resistant renal cell carcinoma." (PMID 34781823, 2021). "DNA damage repair biomarkers, p-DNA-PK and Rad51, were reduced by knockdown of PDIA6, suggesting that PDIA6 promoted DNA damage repair to enhance the resistance of renal cell carcinoma to imatinib." (PMID 34781823, 2021). "The down-regulated p-DNA-PK and Rad51 in A498/R with shPDIA6 transfection was up-regulated by the over-expression of FZD1, indicating that PDIA6 contributed to the imatinib-resistance of renal cell carcinoma through activation of Wnt3a-FZD1 pathway." (PMID 34781823, 2021). "Silencing of PDIA6-induced decreases in p-DNA-PK and Rad51 was restored by over-expression of FZD1, suggesting that PDIA6 might contribute to the resistance of renal cell carcinoma to imatinib through activation of Wnt3a/FZD1 pathway." (PMID 34781823, 2021).
B-cell lymphoma (3 papers, 2022 to 2024). "Since RAD51 has a central role in recombination, SCE formation was assessed in a RAD51-/- DT40 chicken B-cell lymphoma cell line as well, which depends on the expression of a doxycycline-repressible hRAD51 transgene for viability." (PMID 36344511, 2022).
bone marrow failure (3 papers, 2020 to 2025). "Notably, biallelic mutations in certain FA pathway genes, such as FANCS/BRCA1, FANCO/RAD51C, FANCR/RAD51, and FANCM can cause an FA-like disorder that shares the cancer predisposition of classical FA and, in some cases, the associated developmental abnormalities, but lacks bone marrow failure." (PMID 41155398, 2025).
brain cancer (3 papers, 2019 to 2023). A primary or metastatic malignant neoplasm affecting the brain. "For instance, DNA repair protein RAD51 homolog 1 (RAD51) overexpression in breast and brain cancer cells can lead to increased HDR activity, resulting in resistance to chemoradiotherapy." (PMID 32797168, 2020). "In lung and brain cancer cells, the inhibition of DNA-PKcs, an NHEJ pathway protein, rendered cells more sensitive to X-rays than protons and the depletion of RAD51, a HR pathway protein, showed the opposite effect, suggesting a relevant role of HR pathway in the proton-damaged DNA repair." (PMID 31194786, 2019).
cervical tumors (3 papers, 2014 to 2018). "A previous microarray study of paired cervical tumor samples (pre- and post-chemoradiotherapy) reported down-regulation of RAD51 after treatment, supporting the hypothesis that radiation sensitivity is facilitated by a diminished DNA repair response." (PMID 24708616, 2014). "Notably, results showed significantly higher prelamin A and lower RAD51 levels in pR0 compared to pR2 cervical tumors (p<0.05 for both), and the Spearman’s Rank analysis showed a significant negative correlation between the level of the two biomarkers (r= -0.6, p<0.05)." (PMID 29212225, 2017). "On the other hand, previous studies have demonstrated that HPV E7 increases RAD51 (and BRCA1) levels in a transcriptional and potentially posttranscriptional manner, with a downregulation in cervical tumour samples following chemoradiotherapy." (PMID 29212225, 2017). "Increased protein levels of FANCD2, RAD51, BRCA1, and BRIP 1 (BACH1) in NCR compared to CR cervical tumors groups were confirmed on the validation set." (PMID 24708616, 2014). "Our results revealed an increased protein level of FANCD2, RAD51, BRCA1 and BRIP1 in the NCR compared to CR cervical tumor nuclei." (PMID 24708616, 2014). "We observed a significantly increased protein levels of FANCD2, BRCA1, RAD51 and BRIP1 in the nuclei of the NCR compared to the CR cervical tumors." (PMID 24708616, 2014).
fibrosarcoma (3 papers, 2015 to 2023). A malignant mesenchymal fibroblastic neoplasm affecting the soft tissue and bone. "Exosomes were also utilized to transport siRNA against RAD51, which reduced RAD51 expression in cervical and fibrosarcoma cancer cells, resulting in significant cell death in the recipients." (PMID 35813829, 2022). "To characterize the nuclear localization of RAD51, we began with the S33 cell line, a derivative of the human fibrosarcoma line HT1080 that carries an untagged RAD51 expression construct under the control of a doxycycline (dox)-repressible promoter." (PMID 25765654, 2015). "Conversely, previous studies suggested that RAD51 overexpression contributed to genome instability and induced slow-growth phenotypes and increased apoptosis in HT1080 human fibrosarcoma cells." (PMID 37175611, 2023).
head and neck squamous cell carcinoma (3 papers, 2014 to 2022). A squamous cell carcinoma that arises from any of the following anatomic sites: lip and oral cavity, nasal cavity, paranasal sinuses, pharynx, larynx, and salivary glands. "Over-expression of RAD51 protein has been observed in many cancers including include breast, ovarian, pancreatic, head and neck squamous cell carcinoma (HNSCC), prostate, and non-small-cell lung cancer." (PMID 36358700, 2022). "The same study demonstrated a correlation of SMAD4 knockdown with the downregulation of BRCA1 and RAD51 protein expression in head and neck squamous cell carcinoma (HNSCC) as well as increased expression of TβR1 and phospho-SMAD3." (PMID 33418880, 2021).
hereditary cancer (3 papers, 2016 to 2020). Malignant neoplasms occurring in families at a rate greater than that expected by chance and caused by germline mutations in a specific gene. "A prospective cohort of 1021 unrelated cancer cases with clinical suspicion of hereditary cancer was screened for mutations in the following 14 FA genes: FANCA, FANCB, FANCC, FANCD2, FANCE, FANCF, FANCG/XRCC9, FANCI, FANCL/PHF9, FANCM, FANCP/SLX4, FANCQ/ERCC4, FANCR/RAD51 and FANCU/XRCC2." (PMID 32235514, 2020).
hereditary ovarian cancer (3 papers, 2015 to 2019). "The second gene featuring pathogenic variants in our sample, RAD51D (paralog of RAD51), has recently been identified as a moderately penetrant gene in hereditary ovarian cancer." (PMID 28591191, 2017).
malaria (3 papers, 2021 to 2025). Malaria is a serious and sometimes fatal disease caused by a parasite that commonly infects a certain type of mosquito which feeds on humans. "Given that malaria parasites are thought to depend almost exclusively on HR to repair DSBs, and since Rad51 is required for HR in model organisms, we anticipated a near-complete elimination of recovery in the PfRad51Δ line." (PMID 41277688, 2025).
mesothelioma (3 papers, 2021 to 2024). A usually malignant and aggressive neoplasm of the mesothelium which is often associated with exposure to asbestos.
oropharyngeal carcinoma (3 papers, 2021 to 2023). Carcinoma, predominantly squamous cell, arising from the epithelial cells of the oropharynx. "In order to confirm the correlation of the HPV status with cellular and molecular mechanisms underlying favorable prognosis, we investigated γH2AX, RAD51, and PARP1 protein expressions in HPV-positive and HPV-negative cell lines and oropharyngeal carcinoma patient samples." (PMID 34194286, 2021).
Promyelocytic leukemia (3 papers, 2011 to 2023). "Promyelocytic leukemia nuclear bodies (PML-NBs) are important for the assembly and disassembly of protein complexes, including those with RAD51, RPA, and BRCA1 necessary for HRR (for a recent review)." (PMID 21666281, 2011).
prostate tumor (3 papers, 2015 to 2024). "We employed 14 patient-derived tumor graft models pancreatic, lung, and prostate tumor graft models harboring HR mutations (BRCA1/2, CHK1/2, ATM/ATR, PALB2, PARP1/2, RAD51, FANCA/B) to compare LP-184’s potency with PARPi olaparib." (PMID 38630886, 2024). "RAD51 displayed a higher incidence of LOH than BRCA2, which is considered a prostate tumor suppressor." (PMID 26433958, 2015).
pulmonary fibrosis (3 papers, 2018 to 2026). Chronic progressive interstitial lung disorder characterized by the replacement of the lung tissue by connective tissue, leading to progressive dyspnea, respiratory failure, or right heart failure. "Further examination revealed decreased Rad51 expression in the pulmonary fibrosis mouse model induced by intratracheal injection of bleomycin." (PMID 38649802, 2024). "Notably, decreased Rad51 expression was also observed in the bleomycin‐induced mouse pulmonary fibrosis model." (PMID 38649802, 2024).
squamous cervical cancer (3 papers, 2014 to 2022). "In line with our results, previous studies demonstrated increased RAD51 expression in pre-treatment tumor biopsies in non-responsive compared with responsive advanced squamous cervical cancer patients." (PMID 29212225, 2017). "Therefore, our findings demonstrate that baseline FANCD2, RAD51, BRCA1 and BRIP1 nuclear protein expression could have an important role in treatment failure in advanced squamous cervical cancer." (PMID 24708616, 2014).
viral infection (3 papers, 2017 to 2020). "Therefore, it is possible that the recruitment of MRN and RAD51 to the viral genome is another defense against innate immunity, simultaneously preventing MRE11-RAD50 localization to the cytoplasm, and inappropriate processing of host DNA by RAD51 when the MRN complex is disrupted by viral infection." (PMID 32545729, 2020).
acute lymphoblastic leukemia (2 papers, 2013 to 2021). Leukemia with an acute onset, characterized by the presence of lymphoblasts in the bone marrow and the peripheral blood. "Mutations in EBF1 are common in acute lymphoblastic leukemia, and heterozygosity of this gene is associated with increased DNA damage and decreased homologous recombination through decreased Rad51 expression and decreased apoptosis in mice." (PMID 34379776, 2021).
adenoma (2 papers, 2014). A neoplasm arising from the epithelium. "RAD51 mRNA amount was increased in laser-microdissected mammary simple carcinomas when compared to adenomas or non neoplastic mammary gland of the same dog, indicating a genomic instability in RAD51-expressing cells in carcinomas." (PMID 24748173, 2014). "In adenoma vs. normal samples, BRCA2/1 and RAD51 expression was reduced." (PMID 24641873, 2014).
adenovirus infection (2 papers, 2018 to 2020). "RecA has significant homology to eukaryotic Rad51 and its paralogs, enzymes that repair dsDNA breaks in human cells, facilitate homologous recombination, and during adenovirus infection, bind to the E2 DNA binding protein." (PMID 30254627, 2018).
amyotrophic lateral sclerosis (2 papers, 2023 to 2025). Amyotrophic lateral sclerosis (ALS) is a neurodegenerative disease characterized by progressive muscular paralysis reflecting degeneration of motor neurons in the primary motor cortex, corticospinal tracts, brainstem and spinal cord. "Overexpression of RAD51 restores the accumulated DSBs in aged cells and extends the replicative life span of yeast, implying the potential application of H4K20 and RAD51 in curing rDNA-associated human diseases such as amyotrophic lateral sclerosis, and Huntington’s disease." (PMID 37980416, 2023). "Furthermore, SFPQ mislocalization has been observed in neurodegenerative disorders such as Amyotrophic Lateral Sclerosis, Alzheimer’s and Frontotemporal dementia, where its functional loss could contribute to genome instability and neuronal vulnerability through similar RAD51-dependent mechanisms." (PMID 40964404, 2025).
Autoimmunity (2 papers, 2016 to 2018). The occurrence of an immune reaction against the organism's own cells or tissues. "Since sni1 phenotypes are suppressed by mutation of EDS1, we also tested if the involvement of SNI in RAD51 regulation could be linked to sni1 autoimmunity." (PMID 29462140, 2018). "In conclusion, our findings establish an unanticipated role of the nuclear ssDNA-binding capacity of RPA and Rad51 as an innate defence against self DNA and provide novel mechanistic insight into pathways underlying nucleic acid-driven autoinflammation and autoimmunity." (PMID 27230542, 2016). "We provide evidence of sni1 autoimmunity and propose that this autoimmunity underlies some previous misconceptions about the function of SNI1 as a negative regulator of SAR, its involvement in RAD51 regulation, and the accumulation of DNA damage in sni1 loss-of-function mutants." (PMID 29462140, 2018). "Considering the involvement of SNI1 in RAD51 regulation, our observation that transcripts of DDR genes are downregulated in sni1 again fits with a model in which autoimmunity, and not a regulatory function on SNI1, affects the levels of DDR transcripts and RAD51 protein." (PMID 29462140, 2018).